FRMPD3 (FERM and PDZ domain containing 3)
Synonyms: KIAA1817; RP5-1070B1.1
Tractability: Antibody: its Gene Ontology location is reachable by antibodies, with high confidence.
Gene: Protein-coding gene on chromosome X (107,449,652 to 107,605,255, forward strand). Ensembl gene ENSG00000147234.
Subcellular location (Human Protein Atlas): Cytosol; Mitochondria
Pathways (Reactome):
Immune System: Neutrophil degranulation
Gene Ontology:
Molecular function: protein binding
Cellular component: plasma membrane; secretory granule membrane; tertiary granule membrane
Homologues: Orthologues: macaque FRMPD3 (99% identical), pig FRMPD3 (92% identical), mouse Frmpd3 (92% identical), guinea pig FRMPD3 (91% identical), rat Frmpd3 (91% identical), chimpanzee FRMPD3 (86% identical), dog FRMPD3 (83% identical), zebrafish frmpd3 (45% identical), tropical clawed frog frmpd3 (28% identical), Drosophila melanogaster CG42788 (17% identical), Caenorhabditis elegans frm-8 (10% identical). Paralogues in human: FRMPD4 (30% identical), FRMPD1 (18% identical).
Diseases named in the same sentence as FRMPD3 in open-access papers:
FRMPD3 is named in the same sentence as 5 diseases in open-access papers, as found by Europe PMC text mining. Sharing a sentence is not in itself a finding about the gene and the disease. The quoted sentences say what the papers report.
endometrial cancer (1 paper, 2021). Primary or metastatic malignant neoplasm involving the endometrium (mucous membrane that lines the endometrial cavity). "The results of Kaplan–Meier prognostic analysis showed that high expression of the risk-associated genes (B3GAT2, CD3EAP, FRMPD3, LINC01224, LINC02068, LY6H, and NR6A1) is related to poor prognosis in endometrial cancer patients (P < 0.05)." (PMID 33747079, 2021).
epilepsy (1 paper, 2025). A brain disorder characterized by episodes of abnormally increased neuronal discharge resulting in transient episodes of sensory or motor neurological dysfunction, or psychic dysfunction. "In our study, we identified a novel scaffold protein, Frmpd3, and provided insights into the mechanism by which Frmpd3 is involved in epilepsy susceptibility and the regulation of pathological neuronal excitability." (PMID 40699624, 2025). "Here, we investigated the distribution of Frmpd3 in the central nervous system and its potential regulatory role in epilepsy, a neurological disorder characterized by disrupted excitatory–inhibitory balance." (PMID 40699624, 2025). "In this study, we reveal Frmpd3 protein expression in specific mouse brain regions and its probable functions in epilepsy." (PMID 40699624, 2025). "To further explore the changes in Frmpd3 protein levels in epileptic brain tissue, we established a chronic epilepsy animal model via the intraperitoneal injection of PTZ in mice." (PMID 40699624, 2025). "To further explore whether Frmpd3 is involved in the regulation of epilepsy susceptibility, we constructed an AAV9 pAAV-hSyn-EGFP-3xFLAG-WPRESiFrmpd3 vector to knock down Frmpd3 in the hippocampal CA1 neurons of mice." (PMID 40699624, 2025). "The immunofluorescence staining results revealed Frmpd3 protein expression in the PSD, suggesting that Frmpd3 in hippocampal neurons may be associated with epilepsy." (PMID 40699624, 2025). "However, the distribution and function of Frmpd3 in the central nervous system remain unclear, particularly its role in epilepsy." (PMID 40699624, 2025). "The results of the immunofluorescence staining of mouse brain tissues revealed that Frmpd3 was expressed in the cortex, hypothalamus, cerebellum, and hippocampus, among which the hippocampus is an important brain area related to the occurrence and development of epilepsy." (PMID 40699624, 2025).
FRMPD3 also shares sentences with these, for which no sentence is quoted: autism (1 paper); neurological disorder (1); Seizure (1).